NRAS (NRAS proto-oncogene, GTPase)
Diseases named in the same sentence as NRAS in open-access papers (continued):
Sharing a sentence is not in itself a finding about the gene and the disease.
melanoma (continued). "There is an unmet medical need for new targeted therapy opportunities in patients whose tumors harbor an NRAS mutation, occurring in 15–25% of patients with melanoma and producing the activation of Ras/Raf/MEK/ERK signaling pathway." (PMID 35053435, 2022). "Guidelines recommend BRAF V600 and NRAS mutation testing on tumor specimens for resectable or unresectable stage III/IV melanoma." (PMID 35804825, 2022). "This sequencing technology has been used in melanoma research to unravel the clinical phenotypes related to NRAS and BRAF mutations." (PMID 36431075, 2022). "Regarding ERβ, we observed comparable levels in primary melanomas and in NRAS mutated metastatic cell lines, and lower, but well detectable levels in the BRAF mutated primary Me1402/R and metastatic A375M cell lines." (PMID 35371312, 2022). "Activating mutations (i.e., BRAF, NRAS, etc.)are found in both benign and malignant tumors, i.e., nevi and melanoma." (PMID 36077603, 2022). "Melanoma cell lines with NRAS mutations at codon 61 were treated with Amgen Compd A (a pan-RAF inhibitor) and trametinib (a MEK inhibitor) to synergistically suppress cell growth." (PMID 35954441, 2022). "Studies have demonstrated a 3-fold increased risk of death for higher‐risk tumors harboring NRAS or BRAF mutations compared with wild‐type melanomas, after adjusting for other prognostic factors." (PMID 35669434, 2022). "Previous studies demonstrated that NRAS mutations occur more commonly in nodular subtype melanomas than in other subtypes and often develop in the skin with continuous ultraviolet exposure." (PMID 34110110, 2022). "NRAS is commonly mutated in several cancers, and it serves as an important oncogenic driver in melanoma." (PMID 35954441, 2022). "In clinical trials Trametinib was also partially successful in treating melanomas harbouring NRAS mutations." (PMID 36119516, 2022). "Further understanding of melanoma with NRAS mutations will be crucial in developing new management strategies for melanoma patients with NRAS mutations." (PMID 34110110, 2022). "NRAS is an oncogene that is mutated in around 15% to 25% of melanomas, and it is the most frequently mutated driver gene in CMs originated from congenital nevi, by a very long way." (PMID 36143375, 2022). "Although depletion of USP9X reduces tumor growth in melanoma cells carrying BRAF or NRAS mutations, its combination with MAPK pathway inhibitors (vemurafenib or MEKi) has been shown to enhance the therapeutic response." (PMID 35884430, 2022). "Mutations of NRAS (in 15–30 percent of melanoma tumor samples) have been recognized as a vital driver of oncogenesis in melanoma patients." (PMID 36224606, 2022). "RAS family members KRAS and NRAS are frequently mutated in colorectal and pancreas adenocarcinoma, and multiple myeloma and melanoma, respectively." (PMID 35768873, 2022). "BRAF and NRAS are the most frequently affected oncogenes in acral melanomas but at a lower frequency compared to sun-exposed melanomas, whereas KIT mutations are more common in acral melanomas." (PMID 35197475, 2022). "PTEN loss is more often found in BRAF-mutant than in NRAS-mutant melanoma, a finding compatible with PI3K/AKT pathway activation by NRAS but not BRAF mutations, which need an additional hit." (PMID 36614156, 2022). "The incidence of these mutations varies among cancer types such that NRAS mutations in melanomas are almost entirely at the Q61 position." (PMID 36497424, 2022). "Collectively, these results demonstrate that HSPB8 acts both on mutated and wild-type NRAS proteins, and this event is crucial to explain antitumoral effects in melanoma cell lines." (PMID 36400750, 2022). "Of the three RAS isoforms (KRAS, NRAS, and HRAS), activated NRAS mutations are common in melanoma (17%) and hematological malignancy (9.6–19%)." (PMID 36358254, 2022).
melanoma (continued). "The second largest group of melanoma patients, whose tumors harbor a mutation in the NRAS gene, demonstrates only a limited response to targeted therapy with MEK inhibitors." (PMID 36230853, 2022). "Recent studies show that the presence of neuroblastoma RAS viral oncogene homolog (NRAS) mutation can influence cell growth in melanomas." (PMID 34110110, 2022). "The study of NRAS mutation is still under development, so this study selected NRAS mutation melanoma as the research target and studied the use of small-molecule inhibitors for NRAS mutation melanoma." (PMID 35310910, 2022). "The present work has evaluated the overall clinical performance of IdyllaTM Biocartis in the characterization of BRAF/NRAS-mutated melanoma patients, either in radically operated stage III–IV or in locally advanced/metastatic ones." (PMID 35804825, 2022). "Despite the advances in BRAFV600E-mutated melanomas, there is considerably less known about the role of mutant NRAS in reprogramming metabolism in this disease." (PMID 36402789, 2022). "NRAS mutations emerge in about 20% of melanomas and are evenly spread among cutaneous, acral, and mucosal melanomas." (PMID 36614156, 2022). "As the phosphorylation gene of MAPK protein, NRAS has become one of the taxonomic markers of four subtypes of melanoma; moreover, high expression of NRAS is associated with poor prognosis of lung adenocarcinoma." (PMID 34878732, 2022). "Of note, the lower ERα/β ratio observed in metastatic versus primary NRAS mutated melanomas suggests a greater decrease of ERα than ERβ expression." (PMID 35371312, 2022). "Based on the experience with NRAS-mutated melanomas, we initiated therapy with a checkpoint-inhibitor." (PMID 33921303, 2021). "In contrast, common mutations in melanomas such as NRAS and NF1 remain unable to be targeted to date." (PMID 34831002, 2021). "Melanoma arising in giant congenital nevi harbor the NRAS p.Q61 mutation while the BRAF mutation or fusion is infrequent." (PMID 34440462, 2021). "NRAS is an oncogene typically found in melanoma, and multiple targeted therapy agents have been developed for the treatment of NRAS-mutated melanoma." (PMID 35087523, 2021). "Cancer-associated fibroblasts (CAFs) were isolated from a biopsy of cutaneous melanoma metastases (patient diagnosed with MM with an NRAS mutation (Q61R) but a BRAF wild-type)." (PMID 34638245, 2021). "Collectively, despite enormous effort, the exact molecular mechanisms why drug resistance evolves in mutated BRAF or NRAS melanomas remain elusive." (PMID 34063141, 2021). "NRAS mutant melanoma has been demonstrated to be associated with more unfavorable survival than wild-type melanoma in some studies, although heterogeneous situations have been observed in other series." (PMID 34290710, 2021). "In melanoma cell lines with activating NRAS mutations, combination of PI3K or AKT inhibitors with MEK inhibitors has demonstrated synergistic inhibition." (PMID 34571863, 2021). "For example, NRAS-mutated melanoma is a distinct subtype in approximately 5%–20% of patients with melanomas and appears to have a poor prognosis." (PMID 35069558, 2021). "Two patients with NRAS mutant advanced melanoma, including 1 patient with amino acid mutation of Q61R and 1 patient with G12D, achieved a partial response (PR)." (PMID 34290710, 2021). "NRAS mutant melanomas seem associated with worse prognosis and with an increased risk of brain metastases." (PMID 35008245, 2021). "We can also mention a cluster of RAS mutated cell lines, usually NRAS mutated for melanomas (e.g., SK-MEL-2) and KRAS for colorectal cancers (e.g., COLO-678), which are classified by the model as resistant." (PMID 33507915, 2021).
melanoma (continued). "Recently, a study reported that 3D melanoma cells (mutated BRAF and mutated NRAS melanoma cells) were significantly more sensitive than 2D cells to a combined treatment (dabrafenib and trametinib)." (PMID 34638245, 2021). "An additional experiment studied the combinatory inhibition of MEK and pan-RAF, which are both downstream signaling proteins in the MAPK pathway, and showed significant growth inhibition in NRAS-mutated human melanoma cell lines." (PMID 33807778, 2021). "Dual targeting of MEK and Erk5 using Trametinib plus XMD8-92 inhibited the growth of NRAS-mutant melanoma cells and repressed tumor progression in NRAS-mutated melanoma xenografts." (PMID 34946644, 2021). "Approximately 50% and 20%–30% of human melanomas have activating mutation in BRAF or NRAS genes, respectively." (PMID 33804655, 2021). "In a panel of NRAS mutant human melanoma cell lines, we observed an association between the degree of activation of the Rho/MRTF pathway and intrinsic resistance of cells to trametinib-mediated apoptosis." (PMID 33921974, 2021). "Recently, Kelch domain-containing F-Box protein 42 (FBXO42) has been recognized as a factor causing the resistance of NRAS-mutant melanomas to trametinib." (PMID 34063141, 2021). "Type 1 (N1/M1) lesions are characterized by pigmentation-type and MITF gene signatures and prevalent NRAS mutations in M1 melanomas." (PMID 34281234, 2021). "For example, KRAS mutations are highly prevalent in pancreatic cancers (~90%), colorectal cancers (~35%), and lung cancers (~20%), while NRAS mutations exist in melanoma (~20%) and thyroid cancers (~20%)." (PMID 35582307, 2021). "In conclusion, beside SLN positivity, age of the patients, Breslow thickness, lymphovascular invasion, and NRAS mutation of the primary tumor proved to be independent prognostic factors of melanoma progression." (PMID 34209415, 2021). "This pathway is very often activated in melanoma by activating mutations of the oncogene NRAS, loss of expression or function of the tumor suppressor gene PTEN, and activation of receptor tyrosine kinases (RTKs)." (PMID 34680615, 2021). "In a retrospective analysis, compared to melanoma patients with wild-type NRAS, those with NRAS mutations were found to have higher objective response rates and prolonged stable disease in response to ICIs." (PMID 35069558, 2021). "While KRAS mutations are more prevalent in adenocarcinoma, NRAS mutations are more prevalent in melanomas, thyroid cancers, and leukemias." (PMID 34830283, 2021). "Only one patient presented the well characterized BRAFV600E mutation; however, all patients showed NRAS mutations at different sites (G12V, Q61R, A146T, F156L), which is the second-most mutated gene in melanoma." (PMID 34771574, 2021). "Binimetinib (an MEK1/2 inhibitor) and the STK19 kinase inhibitor chelidonine were described to be relatively effective in NRAS-mutated melanomas, although controversies were raised against the efficacy of the STK19 inhibitor." (PMID 34063141, 2021). "MEK/BET combination inhibition can suppress MAPK and checkpoint inhibitor-resistant melanoma in animal models including those exhibiting NRAS mutations." (PMID 32603264, 2021). "Here we describe some of the main molecular mechanisms underlying the resistance to mutated BRAF and NRAS genes in melanomas." (PMID 34063141, 2021). "Melanoma cell apoptosis induced by ECCA was further verified using another melanoma cell line, Mel-Juso, which harbors mutated NRAS and wild-type BRAF genes." (PMID 34103468, 2021). "Due to primary and secondary resistance, MEK inhibitors have shown limited effectiveness in patients with NRAS-mutated melanoma." (PMID 34804979, 2021). "The mutant of BRAF in melanoma patients has predicted a good survival and the NRAS or NF1-mutant subtype of melanoma was associated with poor outcomes." (PMID 34745259, 2021). "KRAS was the most frequently mutated of the three in adenocarcinoma, and NRAS was the most frequently mutated in melanoma." (PMID 34645806, 2021).
melanoma (continued). "In another report, CRISPR RNA-guided deaminase technology was combined with CROP-seq (CRISPR droplet sequencing) technology to introduce mutations in 3 genes of the MAPK pathway in A375 melanoma cells, namely NRAS, KRAS and MAP2K1 (MEK1)." (PMID 33535416, 2021). "A European retrospective multicenter analysis (n = 364) comparing ICI therapy between NRAS mutant and wild-type melanomas showed a shorter median OS in patients with NRAS mutations (21 months compared to 33 months) despite similar response rates." (PMID 34831002, 2021). "The blue-white veil is also a dermoscopic feature of BRAF and NRAS mutated melanomas and carriers of genetic variants in MTAP, as reported in different studies." (PMID 34440462, 2021). "NRAS is mutated in 15–25% of cutaneous melanomas and is the most common driver mutation seen in melanoma arising from giant congenital nevi." (PMID 35008286, 2021). "Melanoma tumors with mutations in NRAS, the second-most commonly mutated oncogenic driver in melanoma, have limited therapeutic targets." (PMID 33921974, 2021). "Putative oncogenic activating mutations in BRAF (with a frequency of 40–60% in melanomas), NRAS, and KIT, as well as gene fusions, can signal through the MAPK and PI3K pathways, leading to uncontrolled cellular growth, proliferation, and survival." (PMID 34831002, 2021). "For a more comprehensive study, this work should be expanded to include other mouse models of melanoma that are driven by NRAS or other mutations." (PMID 35008307, 2021). "This is reflected in mouse models, where melanocyte-specific activation of BRAF or NRAS is insufficient to generate melanomas but can do so when combined with loss of INK4a by mutation or its silencing by activated β-catenin." (PMID 34819350, 2021). "Other common mutations found in melanoma are NRAS (neuroblastoma RAS viral oncogene homolog), c-Kit and CDKN2A (cyclin dependent kinase inhibitor 2A) the latter of which associates with familial atypical multiple mole melanoma syndrome (FAMMM)." (PMID 35127523, 2021). "In 80% of the cases of melanoma or melanocytic nevi, mutations in NRAS or BRAFgenes are observed, which confirms the crucial role of the MAPK pathway." (PMID 34203771, 2021). "Prospective multicenter study of large sample is needed to confirm the role of NRAS mutation in the response to immunotherapy in patients with advanced melanoma." (PMID 34290710, 2021). "KRAS mutations are common in lung adenoma, pancreatic ductal cancer and colorectal cancer whilst NRAS mutations are found in melanoma." (PMID 33367512, 2021). "The MAPK pathway is constitutively active in a large percentage of melanomas because of activating NRAS and BRAF mutations or inactivating NF1 mutations." (PMID 33766731, 2021). "PLA1A mRNA and serum levels were significantly higher in patients with BRAF-mutated melanoma compared to the patients with NRAS-mutated melanoma." (PMID 33723350, 2021). "MEK inhibitors such as bimetinib appear to be a promising treatment option for NRAS-mutated melanomas." (PMID 33947144, 2021). "Mutations in NRAS gene occur in 20–30% of melanomas, at codon 61 for ≈90% of the cases, resulting in a change in amino acid Q61K (45%) and Q61R (35%) while Q61L and Q61H modifications were lower (20%)." (PMID 33804655, 2021). "Mutations of the NRAS GTPase account for 20% of all melanomas and are the second most common driver mutation." (PMID 33746966, 2021). "NRAS-mutated cutaneous melanoma have an unfavorable prognosis as compared to BRAF mutated or wild-type melanoma." (PMID 34071371, 2021). "NRAS mutant melanomas (NEMOs) are reported to be associated with increased risk of visceral and central nervous system metastases in comparison to wild-type cutaneous tumors." (PMID 34571863, 2021). "Hotspot mutations in BRAF and NRAS define the two major subtypes of melanoma that are mutually exclusive, with 50% of patients harboring BRAFV600E mutations and 30% of patients harboring NRAS hotspot mutations." (PMID 33769711, 2021).
melanoma (continued). "BRAF and NRAS mutations are common in benign nevi, suggesting that additional mutations are required to drive melanoma progression in those tumors." (PMID 35008286, 2021). "For example, activating mutations in KRAS/NRAS are frequently accompanied by loss of function of CDKN2A/B in melanoma, lung, pancreatic, and other cancers." (PMID 33769711, 2021). "Activations of the mitogen-activated protein kinase (MAPK) pathway by BRAF and NRAS mutations are more common in low-CSD melanoma (60% and 20%, respectively)." (PMID 34440462, 2021). "NRAS is preferentially mutated in melanoma and acute myeloid leukaemias, while HRAS mutations are rare." (PMID 33562401, 2021). "The sensitivity of SK-MEL-2 cells to combined targeted therapy indicates that the treatment is interesting in NRAS-mutated malignant tumor cells, including melanoma as previously suggested." (PMID 34638245, 2021). "NRAS mutation significantly correlates with worse OS (p = 0.028) and worse melanoma-specific survival (MSS) (p = 0.03) for all cases of mucosal melanomas." (PMID 34571863, 2021). "In our cohort of patients with BRAF-wt melanoma, 22 out of 45 (49%) patients—with known NRAS mutation status—had a NRAS mutation." (PMID 33915880, 2021). "In melanoma, NRAS mutations correlate with the presence of mitoses, lower tumor-infiltrating lymphocyte (TIL) grade, extremity location, thick tumors, and higher AJCC stage." (PMID 34301278, 2021). "NRAS mutations are also found in melanocytic and dysplastic naevi and melanomas with a high mutation load." (PMID 34441278, 2021). "Fang and colleagues recently described the relationship between tumor BRAF/NRAS mutation status, clinical characteristics and response to conventional therapy in patients with melanoma BM." (PMID 33578810, 2021). "The activation of the RAS/RAF/MEK/ERK signaling pathway through NRAS mutations occurs in 15–20% of melanoma cases." (PMID 34831002, 2021). "The potential value of actinic molecular signature in differentiating metastatic undifferentiated melanoma from rare NRAS-mutated NSCLC remains an issue of future studies." (PMID 33506327, 2021). "One melanoma carried a NRAS mutation (p.Q61R), and another melanoma carried a KIT mutation (exon 11)." (PMID 34065883, 2021). "The overall frequency of main mutations in mucosal melanomas is as follows: NRAS (8%), BRAF (6%), neurofibromin 1 (NF1) (14%), KIT (13%), splicing factor 3b subunit 1(SF3B1) (15%)." (PMID 35008570, 2021). "The second largest class of melanoma tumors contain mutations in the neuroblastoma RAS viral (v-ras) oncogene homolog (NRAS) gene." (PMID 35187538, 2021). "Sun-exposure-related melanoma has high melanocyte mutations such as NRAS, neurofibromin 1, KIT, and BRAFnonV600E compared with common mutation BRAFV600E in non-sun-exposed-related melanoma." (PMID 34199951, 2021). "On the molecular level, to date, the only oncogenic driver reported so far is mutation of NRAS (n = 3), underlining a close biological relation to malignant melanoma and neurocutaneous melanosis." (PMID 33921303, 2021). "Metastatic melanoma (MM) is a highly mutated type of cancer and can be classified into four groups depending on the driver mutation observed—mutation in BRAF (~50% of melanomas), NRAS (~30%), NF1 (10–15%) or triple wildtype." (PMID 34066022, 2021). "Certainly, effective diagnostic markers in the treatment of BRAF/NRAS-mutant melanoma are important in the development of a targeted therapy against advanced metastatic melanoma." (PMID 33723350, 2021). "High-CSD melanomas include lentigo maligna type and desmoplastic melanomas, which often have a high mutation burden and can harbor NRAS, BRAFnon-V600E, or NF1 mutations." (PMID 34571969, 2021). "In a study involving 95 dogs, canine cDNA sequencing data for six genes relevant to human melanoma classification detected somatic mutations in the NRAS and PTEN genes at the human hotspot sites, except in BRAF in oral melanomas." (PMID 34504885, 2021).